SNHG6 (small nucleolar RNA host gene 6)
Synonyms: U87HG; HBII-276HG; NCRNA00058
Gene: Long non-coding RNA gene on chromosome 8 (66,895,990 to 66,926,525, reverse strand). Ensembl gene ENSG00000245910.
Gene Ontology:
Biological process: RNA processing
Cellular component: nucleolus
Diseases named in the same sentence as SNHG6 in open-access papers:
SNHG6 is named in the same sentence as 60 diseases in open-access papers, as found by Europe PMC text mining. Sharing a sentence is not in itself a finding about the gene and the disease. The quoted sentences say what the papers report.
hepatocellular carcinoma (35 papers, 2017 to 2025). A malignant tumor that arises from hepatocytes. "For instance, SNHG6 was an oncogene involved in the progression of hepatocellular carcinoma, and loss of SNHG6 can inhibit liver cancer growth by inhibiting cholesterol biosynthesis." (PMID 38194709, 2024). "As a splice variant of the SNHG6 gene, SNHG6 203 has been proven as an oncogenic transcript in hepatocellular carcinoma." (PMID 36247503, 2022). "The pooled result indicated that increased SNHG6 expression was associated with a poor RFS in hepatocellular carcinoma and colorectal cancer (HR = 3.27, 95% CI: 1.42–5.12, p < 0.001; I2 = 0.0%, p = 0.93)." (PMID 32321469, 2020). "Expression and survival analyses demonstrated that, among these predicted lncRNAs, SNHG1, HCG18, NUTM2A-AS1 and ASB16-AS1, and SNHG6 were markedly upregulated in hepatocellular carcinoma and linked to poor prognosis." (PMID 32257949, 2020). "Silencing of SNHG6 halted cell progression and caused cellular death in hepatoma cell lines." (PMID 37735423, 2023). "SNHG6 is significantly upregulated in hepatoma compared to normal liver tissue and has been shown to be a cholesterol effector that accelerates progression from non-alcoholic fatty liver disease (NAFLD) to hepatocellular carcinoma (HCC)." (PMID 37782337, 2024). "Of note, SNHG6 inactivation blocks mTOR signaling and inhibits tumor growth in a patient-derived hepatoma xenograft model." (PMID 37782337, 2024). "SNHG6 behaving as ceRNA in hepatocellular carcinoma exerts carcinogenic influence by modulating different miRNAs." (PMID 37735423, 2023). "High expression of SNHG6 has been found in a variety of cancer tissues (including colorectal cancer, hepatocellular carcinoma, breast cancer, ccRCC, etc.)and can predict a poor prognosis." (PMID 37004005, 2023). "In one of the early report on the subject, SNHG6 was reported to sponge miR-101 in hepatocellular carcinoma cells." (PMID 36212408, 2022). "In this study, we experimentally down-regulated the SNHG6 in two hepatocellular carcinoma cell lines in vitro, and then measured the proliferation, migration and invasion abilities and the apoptotic levels." (PMID 33663502, 2021). "Although the SNHG6/miR-1297 pathway has been manifested to regulate genome-wide hypomethylation in hepatoma cells, the involvement of SNHG6/miR-1297 axis in DDP-resistance of GC is poorly known." (PMID 34821362, 2021). "As a consequence, SNHG6 enhances migration and invasion abilities of hepatocellular carcinoma cells, along with an increase in HIF-1α expression." (PMID 34298879, 2021). "One lncRNA of interest is the oncogenic small nucleolar RNA host gene 6 (SNHG6), which is aberrantly expressed in cancers such as glioma, hepatocellular carcinoma as well as in lung and colorectal cancers." (PMID 34026654, 2021). "We first explored the expression levels of SNHG6 in hepatocellular carcinoma (HCC) tissues, and found an increased SNHG6 level in HCC tissues compared to the non-HCC controls, especially in aggressive HCC cases." (PMID 33663502, 2021). "In hepatocellular carcinoma, SNHG6 lowers DNA methylation through inhibition of S-adenosylmethionine and down-regulation of MAT1A (methionine adenosyltransferase 1A)." (PMID 32318335, 2020). "SNHG6, a validated lncRNA, has been reported to regulate the expression of multiple tumor-related genes in hepatocellular carcinoma, colorectal cancer and breast cancer." (PMID 32226515, 2020). "Accumulating studies have reported the up-regulation of lncRNA SNHG6 in many cancers, such as breast cancer, hepatocellular carcinoma, and gastric cancer." (PMID 32321469, 2020). "We concluded that SNHG6/miR-6509-5p/HIF1A axis functioned in the progression of hepatocellular carcinoma, and could be the promising therapeutic targets during the development of hepatocellular carcinoma drugs." (PMID 33663502, 2021). "UPF1 is upregulated when SNHG6 is knocked down in human hepatocellular carcinoma cell lines." (PMID 33732285, 2021).
hepatocellular carcinoma (continued). "Our studies suggested that lncRNA-SNHG6 could promote the progression of hepatocellular carcinoma by targeting miR-6509-5p, and identified the cell cycle related protein, HIF1A, as the protein effector of the SNHG6/miR-6509-5p axis." (PMID 33663502, 2021). "In xenografts, the growth of hepatocellular carcinoma is suppressed by the downregulation of SNHG6." (PMID 34298879, 2021). "Furthermore, SNHG6 regulated ZEB1 expression by competitively binding miR-101-3p in hepatocellular carcinoma." (PMID 32321469, 2020). "In hepatocellular carcinoma, SNHG6 promotes cell cycle progression and apoptosis evasion." (PMID 32318335, 2020). "SNHG6 was first uncovered to be involved in the regulation of hepatocellular carcinoma." (PMID 32000704, 2020). "Moreover, SNHG6 is reported to play an oncogenic function in many types of tumors, such as hepatocellular carcinoma, gastric cancer, CRC, lung adenocarcinoma, and bladder cancer." (PMID 31516391, 2019). "In the literature, lncRNA SNHG6 has been reported to be differentially expressed in hepatocellular carcinoma (HCC) and may be a potential biomarker for patients with HCC." (PMID 29254165, 2017). "Another recent study explores the role of long non-coding RNA SNHG6 in hepatocellular carcinoma (HCC)." (PMID 37735423, 2023). "In hepatocellular carcinoma (HCC), lncRNA SNHG6, as a molecular sponge of miR-1297, is involved in regulating genome-wide methylation levels." (PMID 33849550, 2021). "SNHG6 (snoRNA host gene 6), a house keeping gene of the 5′ terminal oligopyrimidine family, is identified as a novel oncogene in diverse human cancers, including colorectal cancer, gastric cancer, ovarian clear cell carcinoma, human osteosarcoma and hepatocellular carcinoma." (PMID 33663502, 2021). "SNHG6 is upregulated in hepatocellular carcinoma (HCC) tissues and cell lines, in which it promotes the proliferation, invasion and migration of hepatocellular carcinoma cells, inhibits apoptosis, and induces cell cycle." (PMID 33732285, 2021). "Increased expression of the small nucleolar RNA host gene 6 (SNHG6) has been reported in different cancers, such as hepatocellular carcinoma, colorectal cancer, and lung cancer." (PMID 32518528, 2020). "Among which, small nucleolar RNA host gene 6 (SNHG6) has been identified as an oncogene in gastric cancer, hepatocellular carcinoma, colorectal cancer, glioma and lung adenocarcinoma." (PMID 32884447, 2020). "MiR-26a-5p has already been reported to bind to SNHG6 in CRC, hepatocellular carcinoma and lung adenocarcinoma." (PMID 31516391, 2019). "SNHG6 upregulates the expression of MAT2A, thereby negatively regulating the concentration of SAMe in cells, leading to significant genome-wide hypomethylation of hepatocellular carcinoma, which is a major feature of tumor genesis." (PMID 33849550, 2021). "For example, Chen found that SNHG8 overexpressed in non-small cell lung carcinoma (NSCLC), and Dong found that SNHG8 is an oncogene in human hepatocellular carcinoma, Meng found SNHG6 promotes glioma tumorigenesis in glioma, and Zhu found SNHG4 overexpressed in hepatocellular carcinoma." (PMID 31967298, 2020). "Furthermore, SNHG6 can interact with heterogeneous nuclear ribonucleoprotein L (HNRNPL) and polypyrimidine tract binding protein 1 (PTBP1) to promote the progression of hepatocellular carcinoma." (PMID 37004005, 2023). "Their findings showed that the upregulation of SNHG6 induced epithelial-to-mesenchymal transition (EMT) and promoted tumorigenesis and metastasis in hepatocellular carcinoma (HCC)." (PMID 37735423, 2023). "Small nucleolar RNA host gene 6 (SNHG6), a newfound lncRNA located at chromosome 8q13.1, has been demonstrated to be a potential oncogene involved in the initial and development of various cancers, such as breast cancer, gastric cancer, hepatocellular carcinoma, and colorectal adenocarcinoma." (PMID 31533634, 2019).
colorectal cancer (32 papers, 2019 to 2024). A primary or metastatic malignant neoplasm that affects the colon or rectum. "Although SNHG6 has been reported to be a potential oncogene in colorectal cancer, its association with chromosomal instability and BCNAs has not yet been investigated." (PMID 38791575, 2024). "The overexpression of SNHG6 has been associated with the progression of tumor and poor prognosis in colorectal cancer, gastric cancer, prostate cancer, HCC lung cancer, breast cancer, gliomas and many more." (PMID 37735423, 2023). "Subsequent experiments have demonstrated that SNHG6 promotes growth and metastasis of colorectal cancer, and its upregulation is associated with tumor progression and poor prognosis." (PMID 34414175, 2021). "SNHG6 upregulation is associated with poor prognosis of patients with colorectal cancer." (PMID 35236381, 2022). "In addition, for colorectal cancer, the pooled results also suggested that the elevated SNHG6 expression was associated with LNM (OR = 1.80, 95% CI: 1.11–2.92), DM (OR = 1.92, 95% CI: 1.15–3.20), and TNM (OR = 1.82, 95% CI: 1.22–2.73)." (PMID 32321469, 2020). "Recent studies have shown that SNHG1 promotes immune evasion in breast cancer cells by regulating miRNA, while SNHG6 facilitates colorectal cancer and glioma progression by modulating miR-101-3p expression." (PMID 39530098, 2024). "Conversely, in a study on colorectal cancer, SNHG6 expression was suppressed in tumor cells and as a result cell, proliferation and migration were elevated." (PMID 37735423, 2023). "miR-181 family is reported to be susceptible to SNHG6, and as a result, upregulation of JAK2 by SNHG6 overexpression has been reported to suppress apoptosis in Colorectal Cancer, where JAK2 is a known inhibitor of apoptosis and promoter of cancer growth." (PMID 37735423, 2023). "SNHG6-mediated autophagy can also induce chemoresistance in colorectal cancer cells against 5-fluorouracil, which is an approved drug against CRC." (PMID 37735423, 2023). "A study on colorectal cancers indicated that CRC cells have a higher level of SNHG6 than normal cells." (PMID 37735423, 2023). "As per the published literature, SNHG6 can impact cisplatin resistance in gastric cancer, 5-FU resistance in colorectal cancer, paclitaxel resistance in prostate cancer as well as radio-resistance in cervical cancer." (PMID 36212408, 2022). "In colorectal cancer cells, SNHG6 overexpression occurs due to SP1 stimulation and DNA copy number gains." (PMID 35236381, 2022). "In colorectal cancer, SNHG6 participated in the suppression of pro-apoptosis gene p21 through EZH2, which thus promoted tumor progression." (PMID 33431838, 2021). "Several long noncoding RNAs (lncRNAs) have been reported to induce tumor chemoresistance to 5-fluorouracil (5-FU) such as lncRNA H19 and lncRNA small nucleolar RNA host gene 6 (SNHG6) in colorectal cancer." (PMID 33718194, 2021). "One recent report also revealed that SP1 activation contributed to the high expression of SNHG6 in colorectal cancer cells, which further promoted the progression of colorectal cancer." (PMID 33431838, 2021). "Previous studies have demonstrated that SNHG6 is overexpressed in different kinds of cancers, such as renal cell carcinoma, gastric cancer, breast cancer, and colorectal cancer." (PMID 32321469, 2020). "Among the six-lncRNA signature components, SNHG6 has an effect on tumor progression in various cancer types, such as colorectal cancer, breast cancer, lung cancer, and ESCC." (PMID 32133283, 2020). "SNHG6 has been found to function by sponging microRNAs and to act as an oncogene in gastric cancer, colorectal cancer, and lung adenocarcinoma." (PMID 32974147, 2020). "LncRNA small nucleolar RNA host gene 6 (SNHG6) has been reported to be abnormally expressed in colorectal cancer, osteosarcoma, and breast cancer." (PMID 32782439, 2020). "The SNHG6/hnRNPA1 complex contributes to colorectal cancer metastasis by enhancing aerobic glycolysis." (PMID 33050646, 2020).
colorectal cancer (continued). "In colorectal cancers, it is reported that lncRNA SNHG6 directly combines with the hnRNPA1 complex, which includes hnRNPA2B1 and PTB, and then increases the proportion of PKM2/PKM1." (PMID 33050646, 2020). "SNHG6 is localized preferentially in the cytoplasm by cytoplasmic and nuclear RNA fractions from some cancer cells, such as hepatocellular cells and colorectal cancer cells." (PMID 32518528, 2020). "A recent study showed that SNHG6 facilitated the resistance of colorectal cancer cells to 5-fluorouracil." (PMID 32782439, 2020). "The lncRNA small nucleolar RNA host gene 6 (SNHG6) enhances colorectal cancer cell resistance to 5-fluorouracil (5-FU), promotes autophagy, and inhibits 5-FU-induced apoptosis in vivo." (PMID 32033142, 2020). "SNHG6 expression was upregulated in all six colorectal cancer cell lines (SW-620, HCT-116, DLD-1, HCT-8, HCT-29, and SW-480) compared with the human colorectal epithelial cell line FHC." (PMID 30626446, 2019). "The mechanism by which SNHG6 inhibits apoptosis was investigated and it was found that SNHG6 sequester miR-101-3p which has been previously identified as a tumor suppressor in several cancers such as gastric cancer, colorectal cancer, and cholangiocarcinoma." (PMID 37735423, 2023). "By integrating genomic data from the TCGA database and GTEx database, we found that SNHG6 was highly expressed in a variety of human cancers, including glioma, renal cancer, gastric cancer, colorectal cancer, head and neck squamous cell carcinoma, lung squamous carcinoma and melanoma, etc.." (PMID 37004005, 2023). "SNHG6 enhances glycolysis via the SNHG6/hnRNPA1/PKM axis in colorectal cancer (CRC)." (PMID 36639695, 2023). "Interestingly, the study finds that SNHG6 is downregulated in colorectal cancer tissues, contrasting its upregulation in some other types of cancer." (PMID 37735423, 2023). "SNHG6 is also upregulated in colorectal cancer (CRC) tissues and cell lines." (PMID 33732285, 2021). "Moreover, SNHG6 accelerated the progression of colorectal cancer by activating the TGF-beta/Smad pathway." (PMID 32782439, 2020). "However, in Meng’ study, they verified that SNHG6 was downregulated in colorectal cancer tissues, suppress ETS1 via the PI3K/AKT/mTOR pathway to inhibit CRC cell proliferation and metastasis." (PMID 32518528, 2020). "SP1 is up-regulated in colorectal cancer and positively correlated with SNHG6." (PMID 30626446, 2019). "In addition, the multivariate analysis of the three prognosis factors revealed that SNHG6 expression was an independent prognostic biomarker (HR = 2.48, 95% CI = 1.60–5.86, P = 0.002) for colorectal cancer." (PMID 30626446, 2019). "In addition, we analyzed SNHG6 expression in human colorectal cancer cell lines." (PMID 30626446, 2019). "Accordingly, SNHG6 has been shown to induce EMT leading to increased proliferation/migration/invasion of gastric cancer cells, colorectal cancer cells, pituitary adenoma, glioma and even breast cancer cells." (PMID 36212408, 2022). "Mechanistically, SNHG6 down-regulates the expression levels of miRNA-214 and miRNA-26a/b via sponging to enhance EZH2 expression, leading to colorectal cancer progression." (PMID 35236381, 2022). "Consistently, SNHG6 upregulated EZH2 expression and induced EMT, migration, and invasion by binding to miR-26a in colorectal cancers." (PMID 33050642, 2020). "Several signaling pathways can be activated by SNHG6, including the MAPK and JNK pathway in gastric cancer, PI3K/AKT/mTOR pathway and TGF-β/Smad pathway in colorectal cancer." (PMID 32655318, 2020). "Another study suggests that lncRNA SNHG6 binds to EZH2 to methylate the tumor suppressor p21 promoter region and inhibit its expression, which proliferates colorectal cancer." (PMID 33050646, 2020).
colorectal cancer (continued). "Bioinformatics analysis and dual-luciferase reporter assay implicated that SNHG6 could competitively bind to miR-26a-5p and upregulate the expression of ULK1, the direct target of miR-26a-5p, thereof leading to autophagy activation and 5-FU resistance in colorectal cancer cells." (PMID 33050642, 2020). "In our previous study, we found that the lncRNA SNHG6 was significantly upregulated in CRC and promoted proliferation, invasion and migration in colorectal cancer cells." (PMID 31516391, 2019). "We then detected the genomic copy number levels of SNHG6 in 30 CRC tissue samples, and copy number gains was identified in 30% (9 of 30) colorectal cancer tissues." (PMID 30626446, 2019). "The study also reveals that this inhibition occurs through the targeting of ETS1 via the PI3K/AKT/mTOR pathway and this implies that SNHG6 might act as a tumor suppressor in the context of colorectal cancer, as opposed to its oncogenic role in other cancer types." (PMID 37735423, 2023).